GPR45 (G protein-coupled receptor 45)
Description:
Protein carrier that acts as a regulator of food intake in the paraventricular nucleus of the hypothalamus (PVH) by mediating transport of G(s) into primary cilia (By similarity). Transported into primary cilia of PVH neurons via its association with TULP3 and carries G(s) into the primary cilia to support MC4R activity and activate ADCY3, leading to cAMP production, which signals to suppress appetite (By similarity). Does not act as a canonical G protein-coupled receptor: does not promote the exchange of GDP for GTP on G(s) protein but mediates G(s) translocation into primary cilia (By similarity).
Synonyms: PSP24; PSP24A; PSP24(ALPHA); PSP24-1; PSP24-alpha
Tractability: Small molecule: it belongs to a druggable protein family. Antibody: its Gene Ontology location is reachable by antibodies, with high confidence; UniProt places it where antibodies can reach, with medium confidence; UniProt predicts a signal peptide or a membrane-spanning region.
Target class: Family A G protein-coupled receptor; Membrane receptor
Gene: Protein-coding gene on chromosome 2 (105,241,743 to 105,243,467, forward strand). Ensembl gene ENSG00000135973.
Subcellular location: Cell membrane; Cell projection, cilium membrane
Pathways (Reactome):
Signal Transduction: G alpha (s) signalling events
Gene Ontology:
Molecular function: protein binding; G protein-coupled receptor activity; protein carrier chaperone
Biological process: G protein-coupled receptor signaling pathway; intraciliary anterograde transport; negative regulation of appetite; protein localization to non-motile cilium
Cellular component: ciliary membrane; plasma membrane; membrane
Genetic constraint (gnomAD): Loss-of-function variants: 10 observed, 13.06 expected, observed/expected ratio (o/e) 0.77, 90% interval 0.47 to 1.3. The upper end of that interval is the gene's LOEUF score, 1.3, which puts it in group 5 of 6, group 1 being the genes least tolerant of losing a copy. Missense variants: 440 observed, 521.99 expected, observed/expected ratio (o/e) 0.84, 90% interval 0.78 to 0.91. Synonymous variants: 220 observed, 236.37 expected, observed/expected ratio (o/e) 0.93, 90% interval 0.83 to 1.04.
Homologues: Orthologues: macaque GPR45 (99% identical), dog GPR45 (89% identical), mouse Gpr45 (89% identical), rat Gpr45 (89% identical), guinea pig GPR45 (86% identical), pig GPR45 (84% identical), tropical clawed frog gpr45 (71% identical), zebrafish gpr45 (62% identical). Paralogues in human: GPR63 (53% identical), GPR26 (18% identical), GPR78 (18% identical).
Diseases named in the same sentence as GPR45 in open-access papers:
GPR45 is named in the same sentence as 11 diseases in open-access papers, as found by Europe PMC text mining. Sharing a sentence is not in itself a finding about the gene and the disease. The quoted sentences say what the papers report.
depression (1 paper, 2022). "Results show that the single nucleotide polymorphism variants of the CDH4 intron region (rs78063755), NTRK3-AS1 downstream region (rs57729223), and between LINC01918 and GPR45 (rs2679891) are suggestively associated with depression." (PMID 36704746, 2022). "This study showed that migraine patients with SNP variants in the intron region of CDH4: rs78063755, downstream region of NTRK3-AS1: rs57729223, and the intergenic region between LINC01918 and GPR45: rs2679891 are suggestively associated with depression in the Han Chinese population in Taiwan." (PMID 36704746, 2022).
Infertility (1 paper, 2013). "A single leucine to serine (L148S) mutation in the last residue of the DRY(X)6L motif of human GPR45 causes idiopathic hypogonadotropic hypogonadism (IHH), a disorder characterized by delayed puberty and infertility." (PMID 23667597, 2013).
Obesity (1 paper, 2023). Accumulation of substantial excess body fat. "They reportedly alleviate obesity by inducing sustainable thermogenesis via GPR activation, such as GPR40, GPR43, GPR45 and GPR120." (PMID 36457182, 2023).
cancer (1 paper, 2021). A tumor composed of atypical neoplastic, often pleomorphic cells that invade other tissues. "HHIPL2, XPO1, SALRNA1, ZBTB45, ANP32AP1, ACTR3BP5, LOC100129138, GPR45, and CAB39L gene deletions were associated with non-cancer subjects without FCH (p < 0.05), while RAB9BP1, LOC101928523, and MALRD1 gene deletions were related to non-cancer patients with FCH (p < 0.05)." (PMID 33431054, 2021).
hematological malignancies (1 paper, 2024). "First, Gprotein-coupled receptor 45 (GPR45), to our knowledge, has not been studied in the contextof hematological malignancies." (PMID 39698279, 2024).
GPR45 also shares sentences with these, for which no sentence is quoted: Glucose intolerance (1 paper); hyperprolactinemia (1); leukemia (1); migraine (1); prostate carcinoma (1); type 2 diabetes mellitus (1).